RUNX1T1 (RUNX1 partner transcriptional co-repressor 1)
Description:
Transcriptional corepressor which facilitates transcriptional repression via its association with DNA-binding transcription factors and recruitment of other corepressors and histone-modifying enzymes. Can repress the expression of MMP7 in a ZBTB33-dependent manner. Can repress transactivation mediated by TCF12. Acts as a negative regulator of adipogenesis (By similarity). The AML1-MTG8/ETO fusion protein frequently found in leukemic cells is involved in leukemogenesis and contributes to hematopoietic stem/progenitor cell self-renewal.
Synonyms: AML1T1; CBFA2T1; CDR; ETO; MTG8; ZMYND2; AML1-MTG8
Tractability: Small molecule: it has a high-quality binding pocket. PROTAC: ubiquitination databases record sites on it.
Gene: Protein-coding gene on chromosome 8 (91,954,972 to 92,103,385, reverse strand). Ensembl gene ENSG00000079102.
Subcellular location: Nucleus
Subcellular location (Human Protein Atlas): Nucleoplasm
Gene Ontology:
Molecular function: DNA-binding transcription factor binding; protein binding; transcription corepressor activity
Biological process: negative regulation of DNA-templated transcription; negative regulation of fat cell differentiation; DNA-templated transcription
Cellular component: nuclear matrix; nucleoplasm; nucleus
Genetic constraint (gnomAD): Loss-of-function variants: 4 observed, 49.12 expected, observed/expected ratio (o/e) 0.0814, 90% interval 0.039 to 0.19. The upper end of that interval is the gene's LOEUF score, 0.19, which puts it in group 1 of 6, group 1 being the genes least tolerant of losing a copy. Missense variants: 442 observed, 673.31 expected, observed/expected ratio (o/e) 0.66, 90% interval 0.61 to 0.71. Synonymous variants: 256 observed, 263.04 expected, observed/expected ratio (o/e) 0.97, 90% interval 0.88 to 1.08.
Cancer hallmarks: suppression of growth (promotes); angiogenesis (promotes)
Homologues: Orthologues: dog RUNX1T1 (99% identical), guinea pig RUNX1T1 (99% identical), mouse Runx1t1 (99% identical), chimpanzee RUNX1T1 (96% identical), rabbit RUNX1T1 (96% identical), macaque RUNX1T1 (96% identical), pig RUNX1T1 (96% identical), rat Runx1t1 (95% identical), tropical clawed frog runx1t1 (92% identical), zebrafish runx1t1 (87% identical), Drosophila melanogaster nvy (32% identical). Paralogues in human: CBFA2T3 (71% identical), CBFA2T2 (62% identical).
Diseases named in the same sentence as RUNX1T1 in open-access papers:
RUNX1T1 is named in the same sentence as 104 diseases in open-access papers, as found by Europe PMC text mining. Sharing a sentence is not in itself a finding about the gene and the disease. The quoted sentences say what the papers report.
acute myeloid leukemia (158 papers, 2004 to 2026). Acute myeloid leukemia (AML) is a group of neoplasms arising from precursor cells committed to the myeloid cell-line differentiation. "The fusion oncogene RUNX1/RUNX1T1 encodes an aberrant transcription factor, which plays a key role in the initiation and maintenance of acute myeloid leukemia." (PMID 33483506, 2021). "We describe the largest series of acute myeloid leukemia (AML) cases demonstrating varying degrees of B-cell antigen expression associated with various RUNX1 lesions other than fusion with RUNX1T1." (PMID 40282530, 2025). "Although first noted for its role in neurogenesis, RUNX1T1, in the form of RUNX1-RUNX1T1, has been recently widely researched in association with hematopoiesis and acute myeloid leukemia (AML)." (PMID 35902872, 2022). "Alterations of RUNX1 in acute myeloid leukemia (AML) are associated with either a more favorable outcome in the case of the RUNX1/RUNX1T1 fusion or unfavorable prognosis in the case of point mutations." (PMID 30050054, 2018). "This case is reported due to its novelty in demonstrating the efficacy of avapritinib, a selective KIT inhibitor, in a rare systemic mastocytosis-associated acute myeloid leukemia (SM-AML) patient with non-D816V KIT mutations and RUNX1::RUNX1T1 fusion." (PMID 41473436, 2025). "Runt-related transcription factor 1 (RUNX1)::RUNX1 partner transcriptional co-repressor 1 (RUNX1T1) acute myeloid leukemia (AML) is a subtype of acute leukemia primarily classified as French American British M2." (PMID 38633925, 2024). "For example, the oncogenic fusion protein complex acute myeloid leukemia/RUNX1T1 (AML1-ETO) aberrantly recruits HDAC 1 to AML1 target genes to promote the progression of acute myeloid leukemia." (PMID 39409910, 2024). "In contrast, a truncated RUNX1::RUNX1T1 isoform, generated via alternative splicing at exon 9, can elicit acute myeloid leukemia transformation in murine HSPCs." (PMID 38201282, 2023). "The RUNX1T1 gene was first identified in the fusion transcript AML1/ETO, generated by a translocation between chromosomes 8 and 21, which occurs in 12%‐15% of acute myelogenous leukemia (AML)." (PMID 33084222, 2021). "RUNX1 partner transcriptional co-repressor 1 (RUNX1T1) earned prestige for its fusion with Runt-related transcription factor 1 (RUNX1) in acute myeloid leukemia." (PMID 34540896, 2021). "Loss-of-function mutations in MGA have been commonly identified in several hematological neoplasms, including acute myeloid leukemia (AML) with RUNX1::RUNX1T1, however, very little is known about the impact of these MGA alterations on normal hematopoiesis or disease progression." (PMID 37790524, 2023). "RUNX1/RUNX1T1 is the most common fusion gene found in acute myeloid leukemia." (PMID 33217477, 2021). "The fusion gene RUNX1/RUNX1T1 is oncogenic in acute myeloid leukemia." (PMID 33483506, 2021). "Acute myeloid leukemia (AML) with RUNX1::RUNX1T1 fusion is well known to often demonstrate aberrant upregulation of CD19 expression." (PMID 40282530, 2025). "Core binding factor acute myeloid leukemia (CBF-AML) includes AML cases harboring RUNX1::RUNX1T1 or CBFβ::MYH11 fusion genes, which are classified as a favorable-risk group." (PMID 38802593, 2024). "In this study, we performed an integrated analysis of bulk and single-cell DNA sequencing data of core-binding factor acute myeloid leukemia patients, defined by the presence of a RUNX1::RUNX1T1 or CBFB::MYH11 fusion gene." (PMID 41152985, 2025). "The fusion oncogene RUNX1/RUNX1T1 could reprogram a large transcriptional network to establish and maintain acute myeloid leukemia (AML) via intricate PPI interactions and kinase-driven phosphorylation events in both adult and pediatric patients." (PMID 39822248, 2024).
acute myeloid leukemia (continued). "Additionally, conditions such as acute myeloid leukemia (AML) with RUNX1::RUNX1T1 fusion, AML with CBFB::MYH11 fusion, myeloid/lymphoid neoplasms with eosinophilia and specific gene rearrangements, and the blast phase of chronic myeloid leukemia (CML) must be excluded from the diagnosis." (PMID 41366999, 2025). "RUNX1T1 (Runt-related transcription factor 1, translocated to 1), a myeloid translocation gene (MTG) family member, is usually investigated as part of the fusion protein RUNX1-RUNX1T1 for its role in acute myeloid leukemia." (PMID 35902872, 2022). "In our study, RUNX1T1 is found to be enriched in two molecular functions: transcription corepressor activity and transcription coregulator activity, as well as in the KEGG signaling pathways related to acute myeloid leukemia and transcriptional misregulation in cancer." (PMID 40266928, 2025). "Recurrent gene rearrangements are present in 30–40% of acute myeloid leukemia (AML), and well-described driver fusions sometimes suffice to diagnose leukemias (for example, PML::RARA, or RUNX1::RUNX1T1 among others)." (PMID 37699001, 2023). "The fusion genes CBFB/MYH11 and RUNX1/RUNX1T1 block differentiation through disruption of the core binding factor (CBF) complex and are found in 10–15% of adult de novo acute myeloid leukemia (AML) cases." (PMID 31896782, 2020). "In addition, chromosomal translocations between the EWSR1 and FLI1 loci and between the AML1 (also known as RUNX1) and ETO (also known as RUNX1T1) loci, which are involved in Ewing’s sarcoma and acute myeloid leukemia (AML), respectively, have been generated by CRISPR in human cell lines." (PMID 26060510, 2015). "This last designation is in contrast to the WHO, which still requires blast counts of at least 20% for a diagnosis of acute myeloid leukemia (AML) in the absence of certain specific AML-defining genetic abnormalities (e.g., PML::RARA fusion, RUNX1::RUNX1T1 fusion, etc)." (PMID 39941875, 2025).
leukemia (138 papers, 2004 to 2026). A malignant (clonal) hematologic disorder, involving hematopoietic stem cells and characterized by the presence of primitive or atypical myeloid or lymphoid cells in the bone marrow and the blood. "This was tested using an established murine leukemia model using retroviral expression of RUNX1::RUNX1T1 9a, which encodes a shortened form of RUNX1::RUNX1T1, that induces the rapid development of AML." (PMID 38454121, 2024). "Mga deficiency in RUNX1::RUNX1T1 9 A expressing cells led to a significantly shortened leukemia latency with a median survival of 177 days for controls, 146 days for Mga(±) mice, and 132 days for Mga(−/−) mice." (PMID 38454121, 2024). "Further, co-expression of full-length RUNX1::RUNX1T1 with activated c-KIT mutations efficiently triggered leukemia in vivo upon transplantation of transduced murine HSPCs into mice." (PMID 38201282, 2023). "Core inding factor (CBF) leukemia subtypes, which includes leukemias harboring fusion genes CBFB/MYH11 or RUNX1/RUNX1T1, are associated with younger age and range from 20% in pediatric to less than 5% in older AML patients." (PMID 34947882, 2021). "Despite the causative role of the RUNX1/RUNX1T1 fusion gene in leukaemia initiation, additional genetic lesions are required for disease development." (PMID 27252013, 2016). "Chromosomal translocations involving Runx1t1 are well-documented and have been associated with several types of leukemia." (PMID 23593401, 2013). "The reported mutations of MGA in pediatric RUNX1::RUNX1T1 leukemias are heterozygous, somatic mutations at variable variant allele frequencies and result in the deletion of the MYC-like bHLH domain, potentially resulting in a protein with altered or abolished function." (PMID 38454121, 2024). "This might be the reason why we missed novel recurring but rare mutations in RUNX1/RUNX1T1-rearranged leukemia [CCND2 (6–12%), MGA (8%)]." (PMID 31896782, 2020). "Most of these are recurrent and class-defining in pAML (for example, KMT2Ar, 20.3%; RUNX1::RUNX1T1, 12.4%), whereas we also found fusions recurrent in other leukemias, such as SET::NUP214 (n = 1) or SFPQ::ZFP36L2 (n = 1)." (PMID 38212634, 2024). "This was confirmed in vivo as Mga(±) and Mga(−/−) HSPCs expressing RUNX1::RUNX1T1 9 A rapidly expanded and developed into leukemias characterized by immature GFP+, cKit+ myeloid progenitor-like cells when transplanted into lethally irradiated recipient mice." (PMID 38454121, 2024). "The ELN also stipulates suitable molecular biomarkers, highlighting leukemia initiating variants (e.g., NPM1, CBFB::MYH11, RUNX1::RUNX1T1, PML::RARA) essential in disease monitoring." (PMID 38891959, 2024). "Pathological analysis of the bones (sternum), brain and meninges, liver, and lungs further show that RUNX1::RUNX1T1 9 A expression in Mga(±) and Mga(−/−) HSPCs leads to mice that are more severely infiltrated by leukemia compared to control mice." (PMID 38454121, 2024). "Our data corroborate that the RUNX1/RUNX1T1 fusion reprograms a large transcriptional network to establish and maintain leukemia via intricate protein–protein interactions and kinase-driven phosphorylation events." (PMID 36980682, 2023). "It has been shown that the leukaemia-specific fusion oncoprotein RUNX1/RUNX1T1 represses the expression of NTAL." (PMID 36902005, 2023). "Our data corroborate that RUNX1/RUNX1T1 reprograms a large transcriptional network to establish and maintain leukemia via intricate PPI interactions and kinase-driven phosphorylation events." (PMID 36980682, 2023). "Most of these are recurrent and class-defining in pAML (e.g., KMT2Ar: 20.2%, RUNX1::RUNX1T1: 12.3%), whereas we also found fusions recurrent in other leukemias, such as SET::NUP21427 (n=1) or SFPQ::ZFP36L228 (n=1)." (PMID 37398194, 2023).
leukemia (continued). "In summary, our study provides a detailed overview of cooperating mutations in one of the largest adult CBF leukemia cohorts so far and highlights fundamental differences between CBFB/MYH11- and RUNX1/RUNX1T1-rearranged leukemia." (PMID 31896782, 2020). "Exon 8 frameshift mutations were highly associated with CBFB/MYH11-rearranged leukemia, while point mutations affecting position D816 were correlated with RUNX1/RUNX1T1 leukemia." (PMID 31896782, 2020). "Loss of the Y-chromosome in male patients correlated with improved RFS in univariate analysis in RUNX1/RUNX1T1 leukemia (HR = 0.39, p = 0.047)." (PMID 31896782, 2020). "The cells originating from the PML/RARα-, RUNX1/RUNX1T1- or DEK/NUP214-positive LT-HSCs induced leukemia with a high penetrance of 70%, 50% or 80%, respectively." (PMID 25568664, 2014). "To identify the cell population that maintains the PML/RARα- or RUNX1/RUNX1T1-positive leukemias, we transferred 2×104 cells from leukemic mice, with a tumor load of at least 80%, into sublethally irradiated secondary recipient mice." (PMID 25568664, 2014). "STAT activation can also be regulated by the phosphatase activity of CD45 as shown for RUNX1/RUNX1T1-positive leukemia." (PMID 25568664, 2014). "Key links, which differentiated these two types of leukemia, included the regulation of the fusion protein RUNX1T1." (PMID 16670008, 2006). "Moreover, RUNX1::RUNX1T1 AML cells are addicted to ERG and RUNX1 with a disbalanced expression in favor of RUNX1::RUNX1T1 causing leukemia cell death." (PMID 39857993, 2025). "Notably, the ETO-family transcriptional corepressors, including ETO (also known as RUNX1T1), ETO2 (also known as CBFA2T3) and MTGR1 (also known as CBFA2T2), are all involved in leukemia-causing chromosomal translocations." (PMID 36158200, 2022). "Although HDACs mutations occur also exceptionally rarely in children with AML, myeloid oncoproteins and leukemia-associated fusions can recruit HDACs abnormally, such as EVI1, RUNX1::RUNX1T1 (previously AML1::ETO), so as to block differentiation and maintain the leukemic phenotype of AML." (PMID 36147798, 2022). "Consequently, RUNX1/RUNX1T1 reprograms a massive transcriptional network to establish and maintain leukemia." (PMID 33217477, 2021). "Upon forced overexpression, the WT1 protein interferes with differentiation of myeloid cell lines and cooperates with the fusion protein RUNX1/RUNX1T1 (AML1/ETO) in a rapid induction of leukemia in transgenic mice, clearly demonstrating a leukemogenic role for WT1." (PMID 29152069, 2017). "The RUNX1T1 (ETO) is first identified as a fusion partner to AML1 (RUNX1) in leukemia." (PMID 28640846, 2017). "DEK/NUP214 and RUNX1/RUNX1T1 both induced leukemia with a low efficiency and long latency." (PMID 25568664, 2014). "In support of this hypothesis, the latency of leukemia induced by a viral model of RUNX1::RUNX1T1 9 A was significantly shortened when expressed in both Mga(±) and Mga(−/−) hematopoietic cells, and the resulting leukemic cells displayed a more immature phenotype." (PMID 38454121, 2024). "Collectively, our data highlight MGA as an important regulator of pathways critical for leukemia development, such as MYC activation, cell cycle, and oxidative phosphorylation, and that loss of function mutations identified in patients can functionally cooperate with the RUNX1::RUNX1T1 oncoprotein." (PMID 38454121, 2024). "However, a truncated version of RUNX1::RUNX1T1 was reported to directly induce leukemia in mice." (PMID 38201282, 2023). "Hence, overexpressing RUNX1::RUNX1T1 in human CD34+ as a single genetic element rather models a pre-leukemic phase of AML allowing for the investigation of additional hits to progress to leukemia." (PMID 38201282, 2023). "Furthermore, the TF POU4F1 is known to be overexpressed in RUNX1/RUNX1T1 leukemia." (PMID 36980682, 2023).
leukemia (continued). "Mutations in DHX15 and SMC1A correlated with shorter OS in RUNX1/RUNX1T1 leukemia (DHX15: HR = 3.57, p = 0.02; SMC1A: HR = 6.47, p < 0.001), while point mutations in KIT at position D816 correlated with reduced RFS in RUNX1/RUNX1T1 leukemia (HR = 2.27, p = 0.046)." (PMID 31896782, 2020). "The regulatory networks governing the top deregulated genes in adult and pediatric RUNX1/RUNX1T1 AML patients include several transcription factors, intermediate proteins and kinases, which orchestrate the establishment and maintenance of leukemia." (PMID 36980682, 2023). "Negatively correlated genes such as RUNX1T1 and LEP were reported to have anti-leukemia effects and were also informative for AML prognosis." (PMID 35227274, 2022). "Approximately one from ten thousand RUNX1/RUNX1T1, PML-RARα, or KMT2A-MLLT3 positive newborns will finally suffer from overt leukemia, according to these estimations." (PMID 33803739, 2021). "In mice, WT1 cooperates with the RUNX1/RUNX1T1 (AML1/ETO) fusion gene in the induction of acute leukemia, further emphasizing a role for WT1 in leukemia development." (PMID 29152069, 2017). "Experiments with transgenic mice have shown that RUNX1- RUNX1T1 knock-in led to the expansion of myeloid progenitor cells but did not block their differentiation nor initiate leukemia." (PMID 39272967, 2024). "As mentioned, RUNX1::RUNX1T1 alone was not able to induce leukemogenesis in mice, prompting the question of additional co-activators necessary to induce leukemia in mice." (PMID 38201282, 2023). "When injected into immunocompromised NOD/SCID mice the RUNX1::RUNX1T1 transduced cells were able to engraft but did not elicit leukemia." (PMID 38201282, 2023). "The expression of the RUNX1/RUNX1T1 fusion protein alone is not sufficient to induce leukemia, but it is a complex process which includes the deregulation of various pathways." (PMID 36980682, 2023). "In contrast, RUNX1/RUNX1T1- positive leukemic cells did not re-establish leukemia in secondary recipients." (PMID 25568664, 2014). "In addition, the absence of RUNX1T1 gene expression in leukemia cells obscures the structural and functional organization analysis of the RUNX1-RUNX1T1 fusion gene." (PMID 36520265, 2022). "Further, mice genetically engineered to express AML1/ETO (RUNX1/RUNX1T1) have been shown to have a normal life span and do not develop leukemia at all." (PMID 35565315, 2022). "The L-MC for RUNX1/RUNX1T1 could not be defined because the related leukemia was not retransplantable, indicating that RUNX1/RUNX1T1 does not completely transform HSPCs." (PMID 25568664, 2014).